DEFB115 (defensin beta 115)
Description:
Has antibacterial activity.
Synonyms: DEFB-15
Tractability: Antibody: UniProt places it where antibodies can reach, with medium confidence; UniProt predicts a signal peptide or a membrane-spanning region; its Gene Ontology location is reachable by antibodies, with medium confidence.
Gene: Protein-coding gene on chromosome 20 (31,257,664 to 31,259,632, forward strand). Ensembl gene ENSG00000215547.
Subcellular location: Secreted
Pathways (Reactome):
Immune System: Beta defensins; Defensins
Gene Ontology:
Molecular function: protein binding; membrane destabilizing activity
Biological process: innate immune response; killing of cells of another organism; defense response to Gram-negative bacterium
Cellular component: extracellular region
Genetic constraint (gnomAD): Loss-of-function variants: 7 observed, 8.75 expected, observed/expected ratio (o/e) 0.8, 90% interval 0.45 to 1.49. That is too few expected variants to judge how well the gene tolerates losing a copy. Missense variants: 143 observed, 103.06 expected, observed/expected ratio (o/e) 1.39, 90% interval 1.21 to 1.59. Synonymous variants: 62 observed, 39.07 expected, observed/expected ratio (o/e) 1.59, 90% interval 1.29 to 1.9.
Homologues: Orthologues: chimpanzee DEFB115 (99% identical), macaque DEFB115 (91% identical), pig DEFB115 (57% identical), rabbit DEFB115 (52% identical), rat Defb28 (52% identical), mouse Defb28 (50% identical). Paralogues in human: DEFB118 (27% identical), DEFB121 (27% identical), DEFB116 (26% identical), DEFB123 (25% identical), DEFB104A (24% identical), DEFB104B (24% identical), DEFB119 (24% identical), DEFB128 (24% identical), DEFB129 (23% identical), DEFB135 (23% identical), DEFB108C (22% identical), DEFB124 (22% identical), and 7 more.